PPFIBP2 (PPFIB scaffold protein 2)
Description:
May regulate the disassembly of focal adhesions. Did not bind receptor-like tyrosine phosphatases type 2A.
Synonyms: Cclp1
Tractability: PROTAC: its protein half-life has been measured.
Gene: Protein-coding gene on chromosome 11 (7,513,298 to 7,657,127, forward strand). Ensembl gene ENSG00000166387.
Subcellular location (Human Protein Atlas): Mitochondria
Pathways (Reactome):
Neuronal System: Receptor-type tyrosine-protein phosphatases
Gene Ontology:
Molecular function: identical protein binding; protein binding
Biological process: neuromuscular junction development
Cellular component: extracellular region; cytosol; presynaptic active zone; presynapse
Genetic constraint (gnomAD): Loss-of-function variants: 107 observed, 113.08 expected, observed/expected ratio (o/e) 0.95, 90% interval 0.81 to 1.11. The upper end of that interval is the gene's LOEUF score, 1.11, which puts it in group 4 of 6, group 1 being the genes least tolerant of losing a copy. Missense variants: 1,117 observed, 1,044.1 expected, observed/expected ratio (o/e) 1.07, 90% interval 1.02 to 1.12. Synonymous variants: 385 observed, 390.49 expected, observed/expected ratio (o/e) 0.99, 90% interval 0.91 to 1.07.
Homologues: Orthologues: chimpanzee PPFIBP2 (99% identical), macaque PPFIBP2 (96% identical), rabbit PPFIBP2 (93% identical), dog PPFIBP2 (92% identical), pig PPFIBP2 (90% identical), rat Ppfibp2 (90% identical), mouse Ppfibp2 (89% identical), guinea pig PPFIBP2 (87% identical), tropical clawed frog ppfibp2 (64% identical), zebrafish ppfibp2a (50% identical), Caenorhabditis elegans hlb-1 (27% identical), Drosophila melanogaster Liprin-beta (27% identical), and 1 more. Paralogues in human: PPFIBP1 (49% identical), PPFIA3 (25% identical), PPFIA1 (25% identical), PPFIA2 (25% identical), PPFIA4 (25% identical).
Diseases named in the same sentence as PPFIBP2 in open-access papers:
PPFIBP2 is named in the same sentence as 16 diseases in open-access papers, as found by Europe PMC text mining. Sharing a sentence is not in itself a finding about the gene and the disease. The quoted sentences say what the papers report.
prostate carcinoma (6 papers, 2008 to 2024). A carcinoma that arises from epithelial cells of the prostate gland. "Germline loss-of-function mutations of PPFIBP2 have been associated with shorter survival in prostate cancer." (PMID 38200428, 2024). "We identify two independent susceptibility loci for prostate cancer at 11p15.4 (rs12791447, P=3.59 × 10−8; PPFIBP2) and 14q23.2 (rs58262369, P=6.05 × 10−10; ESR2)." (PMID 26443449, 2015). "Mutations in PPFIBP2 were involved in pathogenesis of prostate cancer, but alteration in this this gene may be important for the advancement of GBM." (PMID 31137733, 2019). "In the meta-analysis of GWAS, we identified two novel loci associated with prostate cancer, rs58262369 at 14q23.2 (ESR2) and rs12791447 at 11p15.4 (PPFIBP2)." (PMID 26443449, 2015). "PPFIBP2 is a novel gene in the LAR protein-tyrosine phosphatase-interacting protein (liprin) family that has been reported to be an independent prognostic biomarker in prostate cancer and thyroid cancer." (PMID 35912229, 2022). "In TCGA prostate cancer data, rs12791447 acted as an eQTL for PPFIBP2 and NLRP14, which was consistent with the expression levels of blood-related eQTL results for PPFIBP2." (PMID 26443449, 2015). "A 5-gene recurrence predictor of prostate cancer contains KLF6, three common ARACNe-based predictions between MYC and KLF6 (FOS, JUNB and ZFP36), and PPFIA3, which is functionally related to another predicted target of KLF6 (PPFIBP2)." (PMID 18190704, 2008).
endometrial carcinoma (2 papers, 2011 to 2015). A malignant tumor arising from the epithelium that lines the cavity of the uterine body. "While no functional studies on PPFIBP2 have been published, it was reported as a potential biomarker for endometrial carcinomas." (PMID 21955916, 2011).
diabetes (1 paper, 2025). "Furthermore, a number of genes in this set (Peak1, Astn2, Bcar1, Ctnnal1, Ppfibp2) is associated with significant diabetes-related risk loci." (PMID 40667025, 2025).
metastatic melanoma (1 paper, 2021). A melanoma that has spread from its primary site to another anatomic site. "In addition, PPFIBP2-BRAF fusion has been reported in metastatic melanoma patient and PPFIBP2-RET fusion in papillary thyroid carcinoma has shown to lead to the activation of mitogen-activated protein kinase (MAPK) pathway and growth–promoting properties." (PMID 34654889, 2021).
neck cancers (1 paper, 2021). "The protein encoded by PPFIBP2 is liprin-β2; previous studies have shown that low levels of liprin-β2 is associated with a poor prognosis for urothelial, renal, prostate, lung, head, and neck cancers." (PMID 34589112, 2021).
prostate tumours (1 paper, 2015). "The mRNA levels of PPFIBP2 and ESR2 are differentially expressed in prostate tumours and paired normal tissues." (PMID 26443449, 2015).
tumor (23 papers, 2013 to 2025). "Higher expression levels of PPFIBP2 and DENND2D are known to be associated with lower levels of tumor invasiveness and a better prognosis; our present findings were consistent with these earlier observations." (PMID 34589112, 2021). "We also found that the expression level of PPFIBP2 was significantly lower in tumour tissues than in normal tissues in TCGA data set (Pt-test=1.89 × 10−10)." (PMID 26443449, 2015). "cg00478851 is present within a distance of 1500 base pairs from the TSS of PPFIBP2, in a north shore of the closest CpG island; it has HR values of 3.6 and 2.5, respectively, in the malignancy and metastasis signatures, showing its importance for both tumor initiation and metastasization." (PMID 35606887, 2022). "TXNIP, TUSC2, PPFIBP2, GALNT10 and MAP2K3 demonstrated varying degrees of methylation on their promoter regions in normal mucosa, normal salivary rinses and HNSCC tumor samples respectively." (PMID 23403885, 2013).
cancer (8 papers, 2011 to 2025). A tumor composed of atypical neoplastic, often pleomorphic cells that invade other tissues. "The chromosome 11 peak (rs12362545, p-value=1.24e–06) is located in the PPFIA binding protein 2 (PPFIBP2) gene, which plays a role in axon guidance and neuronal synapse development and has previously been implicated in cancer development." (PMID 38224499, 2024). "By utilizing pan-cancer analysis, we found that microsatellite instability was inversely correlated with PPFIBP2, which further clarifies the innate immune-related mechanism in TSCC." (PMID 35912229, 2022). "Pan-cancer analysis explored differences of PLAU and PPFIBP2 in multiple cancers, as well as the correlation between immune cells and hub genes." (PMID 35912229, 2022).
PPFIBP2 also shares sentences with these, for which no sentence is quoted: cholangiocarcinoma (11 papers); breast carcinoma (2); hepatoblastoma (1); non-small cell lung carcinoma (1); osteosarcoma (1); papillary thyroid carcinoma (1); pituitary tumor (1); thyroid cancer (1).